MXRA8 (matrix remodeling associated 8)
Diseases named in the same sentence as MXRA8 in open-access papers (continued):
Sharing a sentence is not in itself a finding about the gene and the disease.
kidney tumor (1 paper, 2022). "Moreover, by controlling the inhibitory impact of ZAP in kidney tumor, MXRA8 expression showed an obvious positive correlation with the sensitivity of tumor tissues to OVM treatment." (PMID 35393389, 2022). "Overall, the ex vivo culture data showed the safety and an overall inhibitory effect of OVM on several tumor types and further provided evidence for using the combination of MXRA8 and ZAP as a pair of predictive biomarkers in OVM therapy in liver and kidney tumors." (PMID 35393389, 2022). "Similarly, by using RT-qPCR, seven kidney tumor patients were divided into MXRA8+/ZAP− (patient No. 1, 2, 6, and 7) or MXRA8+/ZAP+ (patient No. 3, 4, and 5) group." (PMID 35393389, 2022).
lymph node metastasis (1 paper, 2021). "Finally, we performed a LASSO logistic regression analysis of the gene expression matrix of seven of the THCA cohort from the TCGA database by the presence or absence of lymph node metastasis to finalize the risk scores constructed for the five most relevant genes (EVA1A, SERPINA1, FN1, TNC, MXRA8)." (PMID 35141140, 2021).
metastatic tumors (1 paper, 2022). "Thus, in two different cell lines, MXRA8 is elevated in aggressive, metastatic tumors expressing low miR-200s." (PMID 35456497, 2022).
prostate carcinoma (1 paper, 2024). A carcinoma that arises from epithelial cells of the prostate gland. "Our findings indicate that MXRA8 is overexpressed in prostate cancer tissue and its knockout leads to a significant reduction in proliferation, invasion, migration, and ROS generation capacity of PC-3 cells." (PMID 38441550, 2024). "Taken together, our findings provide valuable insights into the potential therapeutic targets for prostate cancer treatment by targeting MXRA8." (PMID 38441550, 2024). "This study aimed to investigate the potential role of MXRA8 in prostate cancer cells." (PMID 38441550, 2024). "Additionally, our investigation of MXRA8 in prostate cancer showed significant upregulation of this gene in the disease as confirmed by PCR and immunohistochemistry." (PMID 38441550, 2024). "Next, we investigated the function of MXRA8 gene in prostate cancer." (PMID 38441550, 2024). "Additionally, we identified a novel oncogene MXRA8 in prostate cancer." (PMID 38441550, 2024). "Firstly, we evaluated the expression profile of MXRA8 in both prostate cancer tissue and adjacent normal tissues using PCR, immunohistochemistry and western blot techniques, where we observed a significant upregulation of MXRA8 in prostate cancer samples as compared to their normal counterparts." (PMID 38441550, 2024).
sarcoma (1 paper, 2025). A usually aggressive malignant neoplasm of the soft tissue or bone. "Similarly, mesenchymal genes with high expression in STS, like MXRA8, could be combined with genes present in normal stromal cells but not in sarcoma cells as ADRB3." (PMID 40814001, 2025).
systemic lupus erythematosus (1 paper, 2025). An autoimmune multi-organ disease typically associated with vasculopathy and autoantibody production. "Given their absence in controls and potential functional relevance, and the limited prior research on their roles in SLE, we propose MXRA8, NADK, POLR3GL, and UBXN11 as candidate genes for further investigation in the context of systemic lupus erythematosus." (PMID 40777011, 2025).
triple-negative breast carcinoma (1 paper, 2023). An invasive breast carcinoma which is negative for expression of estrogen receptor (ER), progesterone receptor (PR), and human epidermal growth factor receptor 2 (HER2). "Our previous work implicated MXRA8 in the growth and metastasis of triple-negative breast cancer (TNBC)." (PMID 37762032, 2023).
infection (20 papers, 2019 to 2025). The state of being infected such as from the introduction of a foreign agent such as serum, vaccine, antigenic substance or organism. "Mutations in some of the tested MXRA8 contact residues were associated with reduced binding and infection." (PMID 36647825, 2023). "Mxra8 also is required for arthritogenic alphavirus pathogenesis, as infection in vivo was inhibited with blocking Mxra8-Fc treatment, anti-Mxra8 antibodies, or in Mxra8-deficient mice." (PMID 33091085, 2020). "Mouse MXRA8 was more potent than human MXRA8 at inhibiting infection, consistent with prior work showing stronger binding of the CHIKV envelope proteins to mouse versus human MXRA813,50,51." (PMID 40909667, 2025). "First, we confirmed that both soluble human and mouse MXRA8-Fc fusion proteins inhibited infection of 293T-MXRA8 cells by pseudovirus expressing the CHIKV envelope proteins." (PMID 40909667, 2025). "Additional studies will be required to clarify the relative roles of WEEV binding to PCDH10 or MXRA8 in infection of avian hosts." (PMID 39048821, 2024). "Conversely, knockout of MXRA8 in Hs 578 T cells, a cell model with a high level of MXRA8 expression, reduced the difference in the infection rate between M1-GFP and M1-E2M." (PMID 37296165, 2023). "In 293T cells, exogenous Mxra8, TIM-1, and L-SIGN all similarly enhanced CHIKV infection, while only Mxra8 promoted infection in HAP1 cells." (PMID 36743418, 2023). "Ectopic expression of MXRA8 in HeLa cells resulted in a much greater increase in the infection rate for M1-E2M than for the parental virus." (PMID 37296165, 2023). "Consistently, knock-down of ZAP significantly promoted the infection of OVM in HeLa-MXRA8 and LoVo-MXRA8 cells, while exerted limited effect on LoVo and HeLa cells with lower MXRA8 expression." (PMID 35393389, 2022). "Expression of MXRA8 is an important determinant of the infection efficiency of different cell lines." (PMID 34063936, 2021). "Expression of either human or hamster MXRA8 resulted in a significant increase in CHIKV infection of BHK-21/WI-2, thus confirming that the reduced infection was caused by reduced MXRA8 expression." (PMID 34063936, 2021). "Fibroblasts are known to be permissive to CHIKV and the infection is MXRA8-dependent, however our data cannot exclude a role for Axl in this cell line." (PMID 34359995, 2021). "The requirement of sulfated GAGs for CHIKV binding and infection was inversely correlated with the levels of Mxra8 expression." (PMID 32999033, 2020). "Mxra8 is expressed on the surface of epithelial, mesenchymal, and myeloid cells, all of which are targets of infection by arthritogenic alphaviruses." (PMID 33091085, 2020). "However, disruption of the predicted interspike contact in duck D1 had no impact on SINV infection, suggesting these interspike contacts, crucial for other alphaviruses, are less important for WEEV complex member infection mediated by duck MXRA8." (PMID 40733635, 2025). "Whereas LCMV can use α-dystroglycan that is expressed on DCs as a receptor to facilitate entry and infection, MXRA8, a primary receptor for RRV, CHIKV, and other arthritogenic alphaviruses, is not expressed on DCs, although other receptors may exist." (PMID 39535221, 2024). "Fibroblasts are permissive for CHIKV and the infection appears to be predominately Mxra8-dependent." (PMID 36743418, 2023). "MXRA8-deficient primary fibroblasts sustained reduced CHIKV infection in cell culture, and MXRA8-deficient mice showed markedly reduced infection and swelling of musculoskeletal tissues after inoculation with CHIKV, MAYV, RRV, or ONNV." (PMID 36647825, 2023).
infection (continued). "Using the Fc-Mxra8 fusion protein or anti-Mxra8 monoclonal antibody as treatment, in vitro infection by MAYV, CHIKV, Ross River virus, O’nyong nyong virus (ONNV), and Barmah Forest virus was reduced." (PMID 36016409, 2022). "Additionally, mice (C57BL/6) infected with CHIKV and ONNV and treated with Fc-Mxra8 fusion protein or anti-Mxra8 blocking antibodies had reduced infection and disease signals (foot swelling)." (PMID 36016409, 2022). "Moreover, pre-incubation with MXRA8 protein significantly reduced OVM infection in MXRA8-expressing cells in a dose-dependent manner, while not directly affecting the intracellular replication of OVM through viral RNA transfection." (PMID 35393389, 2022). "Genetically altering mouse or human Mxra8 resulted in diminished infection, conversely, overexpression of Mxra8 in cell lines increased infection rates by CHIKV, ONNV, MAYV and RRV." (PMID 33922370, 2021). "MXRA8 also acts as a receptor for infection by the alphaviruses Mayaro, Ross River and O’nyong nyong virus." (PMID 34063936, 2021). "The low expression of Mxra8 and CS on HapI cells compared to U-2 OS cells may influence the observed differences in residual binding and infection." (PMID 32999033, 2020). "Upon human infection via mosquito bite, CHIKV enters the bloodstream, where its envelope glycoproteins engage the human host receptor MXRA8 (also known as DICAM, ASP3, or Limitrin) to mediate viral entry." (PMID 41451210, 2025). "The high-resolution structural analysis of virus-receptor complexes (MXRA8-CHIKV, LDLRAD3-VEEV) along with detailed molecular analysis (SFV/EEEV-VLDLR) has enabled the generation of soluble decoy receptors that inhibit infection in cell culture and animals." (PMID 36647825, 2023). "Ectopically expressing MXRA8 on HeLa and HT29 cells resulted in significantly elevated infection rates of OVM, while the infection rate of OVM was largely decreased in ΔMXRA8 Hs578T and HepG2 cells and further restored with MXRA8 trans-complementation." (PMID 35393389, 2022). "The results demonstrated that the infection rate of OVM was reduced on Hs578T and HepG2 ZAP overexpressing cells, and the infectivity was further weakened on cells with both MXRA8-KO and ZAP overexpression." (PMID 35393389, 2022). "The ectodomain of MXRA8 is composed of 2 Ig-like domains that interact with E2-E1 heterodimers to facilitate CHIKV attachment and infection of cells in culture." (PMID 34063936, 2021). "Introduction of this sequence into murine Mxra8 abolishes binding to virus particles and reduces CHIKV pathogenesis in vivo, whereas removal of the insertion in Bovinae Mxra8 enhances binding and infection." (PMID 33091085, 2020). "As expected, rVSVΔG-EBOV infection was enhanced in TIM-1+ 293T cells but Mxra8 did not enhance infection in any of the cell lines." (PMID 36743418, 2023). "CHIKV infection was efficiently blocked with Mxra8 antibodies, whereas the addition of HS did not significantly alter infection." (PMID 36743418, 2023). "To investigate the requirement of HS for efficient CHIKV cell binding and infection when Mxra8 and CS are absent, we used human haploid HapI cells." (PMID 32999033, 2020). "Interestingly, in MXRA8−/− mice, low levels of RRV replication were observed in the present and previous studies, indicating other entry mechanisms were employed by RRV during infection." (PMID 37036079, 2023). "CHIKV entry into HAP1 cells was enhanced with exogenous Mxra8, but not TIM-1, suggesting Mxra8 can enhance entry during a short infection time above the level provided by the naturally produced GAGs." (PMID 36743418, 2023). "While the presence of Mxra8 clearly enhances CHIKV infection in some cells, it is not required for infection in many cell lines." (PMID 36743418, 2023). "Overall, these data indicate that CHIKV requires HS for binding to and infection of HapI cells and emphasize the importance of HS as a CHIKV attachment factor when other ligands such as CS or Mxra8 are absent." (PMID 32999033, 2020).
infection (continued). "Moreover, the requirement of specific GAGs for CHIKV binding and infection of cells with various levels of GAG and Mxra8 expression has not been defined." (PMID 32999033, 2020). "Additionally, the residual binding to and infection of HapI B3GAT3−/− cells, which express little to no GAGs or Mxra8, suggest the presence of an unidentified cell surface molecule engaged by CHIKV or a route of viral entry other than receptor-mediated endocytosis." (PMID 32999033, 2020).
tumor (14 papers, 2014 to 2025). "The pathway analysis of differentially expressed genes in control and MXRA8-knockout tumors suggests that the loss of MXRA8 influences the interaction between tumor cells and the tumor microenvironment." (PMID 37762032, 2023). "Loss of MXRA8 expression delayed tumor development and metastasis in a xenograft model, thus providing the first evidence that reducing MXRA8 can suppress TNBC metastasis." (PMID 37762032, 2023). "However, the loss of MXRA8 significantly delayed tumor development and reduced metastatic dissemination to the lungs in a xenograft model." (PMID 37762032, 2023). "The widely high expression of MXRA8 in multiple solid tumors uncovered in this study might also hint a causative role in tumor progression, which may further help link predictive biomarkers of OVs to tumor pathogenesis." (PMID 35393389, 2022). "Our findings demonstrate for the first time that MXRA8 regulates the progression of human TNBC possibly through influencing the interaction of tumor cells with their microenvironment." (PMID 37762032, 2023). "The re-expression of the miR-200c/141 cluster in MDA-MB-231 cells reduced MXRA8 expression as well as tumor growth and metastasis in vivo." (PMID 37762032, 2023). "MXRA8 levels are associated with cancer immunity, and ICI is changing the treatment paradigm for many cancers, with adequate infiltration of tumor-reactive CD8+ T cells a prerequisite for the ICI response." (PMID 36703779, 2022). "Pan-cancer analysis showed that MXRA8 is abundant in most solid tumors and is highly expressed in tumor tissues compared with adjacent normal ones." (PMID 35393389, 2022). "Compared to the group with high ZAP expression, tumor inhibition rate in MXRA8+/ZAP− was significantly increased under high dose of OVM treatment." (PMID 35393389, 2022). "Although our results had shown a dominant role of MXRA8 in OVM’s oncolysis in several tumor models, interestingly, the regular and even ectopic expression of MXRA8 in normal cells had a negligible impact on the sensitivity to OVM." (PMID 35393389, 2022). "Meanwhile, MXRA8 expression was strongly correlated with tumor malignancy, metastasis, recurrence, and immunosuppressive microenvironment." (PMID 36703779, 2022). "KEGG pathway gene sets and GSVA analysis of hallmark in MXRA8 high and low expression samples from GSE39582 and TCGA datasets revealed that tumor metastasis-related pathways enrichment in the MXRA8 high group." (PMID 36703779, 2022). "The results showed that most of the liver (89.74%, n = 90) and all breast (100%, n = 39) tumor tissues were observed with MXRA8 positive staining, and MXRA8 in liver tumor is upregulated compared to liver normal tissues." (PMID 35393389, 2022). "The protein expression of MXRA8 is negatively correlated with the stromal and immune scores but positively with tumor purity." (PMID 36703779, 2022). "In terms of tumor progression, several studies have reported that high expressions of MXRA8 had poor overall survival (OS) in kidney renal clear cell carcinoma patients and is correlated with tumor microenvironment in esophageal squamous cell carcinoma." (PMID 35281049, 2022). "MXRA8 expression was strongly correlated with tumor malignancy, metastasis, recurrence, and immunosuppressive microenvironment." (PMID 36703779, 2022). "The metastatic tumor cells expressed high levels of MXRA8 compared to the adjacent normal lung tissue." (PMID 35456497, 2022). "We observed an obvious negative correlation between the oncolytic ability of OVM and ZAP expression in MXRA8-expressing tumor cells but not in MXRA8-deficient tumor cells." (PMID 35393389, 2022). "Further study in cancer cell lines and patient-derived tumor tissues revealed that the tumor selectivity of OVM is predominantly determined by a combinational effect of the cell membrane receptor MXRA8 and the intracellular factor, zinc-finger antiviral protein (ZAP)." (PMID 35393389, 2022).